CD4 (CD4 molecule)
Diseases named in the same sentence as CD4 in open-access papers (continued):
Sharing a sentence is not in itself a finding about the gene and the disease.
AIDS (continued). "Unlike HIV-1 encephalitis that may complicate late untreated HIV-1 infection, neurosymptomatic escape usually develops in individuals with blood CD4+ T lymphocyte counts above the 200 cells per μL threshold defining AIDS, and CD8+ T cell infiltration may be very prominent." (PMID 32697807, 2020). "Due to the systemic immunodepression, patients with AIDS are susceptible to opportunistic pathogens, and one of the most frequent is CMV that, in approximately 85% of cases, induces CMV-R, particularly in patients presenting other risk factors (e.g. CD4+ cells count < 50)." (PMID 33122781, 2020). "Moreover, the levels of immune activation predict the magnitude of CD4+ T-cell depletion better than viral loads in HIV-infected patients, and are associated with disease progression, the development of AIDS-defining and non-AIDS conditions, and mortality." (PMID 31447862, 2019). "Thus, we speculate that expansion of activated monocyte subsets and low CD4/CD8 ratios could be driving factors for non-AIDS defining illnesses in our LTNP cohort." (PMID 31867010, 2019). "This approach could be used to evaluate the disease progression of patients with HIV/AIDS, where multistate Markov models based on CD4 cell counts have previously been used or modelling health assessment questionnaire (HAQ) scores in patients with psoriatic arthritis." (PMID 30674285, 2019). "Despite the percentage of AIDS-related deaths in the ART-CC being lower than in Spectrum, the cause of death-coding system in the ART-CC may over-estimate AIDS-related deaths because of the use of indirect evidence of AIDS, such as low CD4+ counts within the year before death." (PMID 31800404, 2019). "The median time to AIDS from the first recorded CD4% value was 11.7 years (95% confidence interval [CI], 7.3 to 16.1 years) for faster progressors with a faster CD4% decline and 16.8 years (CI, 12.3 to 21.3 years) for slower progressors with a slower CD4% decline (P = 0.008 [log rank test])." (PMID 30622192, 2019). "In this study, we observed a low CD4/CD8 ratio among the study cohort, particularly among 139 (58%) individuals with extremely low ratio that might predispose this group to a higher risk of non-AIDS morbidity and mortality." (PMID 30755782, 2019). "The results reveal that, although HIV/AIDS patients generally take longer to reach a normal CD4 cell count compared to the time taken to reach an undetectable viral load, patients below the age of 45 years have reduced risks of mortality once the CD4 cell count is normal." (PMID 30770728, 2019). "However, a significant number of cART-treated patients fail to achieve substantial increases in the CD4+ T-cell count, remaining at risk of progression to acquired immune deficiency syndrome (AIDS), non-AIDS morbidities, and death." (PMID 31208153, 2019). "CD4 and CD8 cells are specific types of T lymphocytes, and their relative populations are important for evaluating the stage of human immunodeficiency virus (HIV) infection or acquired immune deficiency syndrome (AIDS), as well as for evaluating the efficacy of antiretroviral treatment." (PMID 31248115, 2019). "The opposing effect of LY6E on HIV infection may have implications for understanding the role of LY6E in the early stage of HIV transmission in monocytes/MDMs/DCs, where CD4 expression is low, in contrast to the late stage of AIDS pathogenesis where the virus predominantly infects high-CD4 T cells." (PMID 31684192, 2019). "Our more systematic exploration of different windows of earlier ART initiation and different cut-off points of CD4 count using change-point analysis showed that there is no strong association between the rate of a new AIDS event and different start times or different levels of CD4 count at baseline." (PMID 30707696, 2019).
AIDS (continued). "As CD4+ T cell count is an important indicator that can reflect the status of cellular immune function, the negative correlation between miR-146a and CD4+ T cell counts suggests that miR-146a may be associated with the AIDS disease progression." (PMID 31827152, 2019). "Furthermore, a low CD4/CD8 is associated with a higher risk of non-AIDS-related morbi-mortality, including incidence of non-AIDS malignancies, among ART-treated HIV-infected patients despite long-term viral suppression." (PMID 30346965, 2018). "Considering that CD4 cell counts observed for patients with AIDS exhibiting CR (1 to 368 cells/mm3, median = 31) were very different from patients with AIDS without CR (4–1164 cells/mm3, median = 588), one may argue that CD4 cell count could be a confounding variable." (PMID 30245869, 2018). "Among HIV-positive individuals, low CD4+ : CD8+ ratio has been associated with higher levels of immunosenescence and inflammation, although the results regarding whether a low or inverted CD4+ : CD8+ ratio predicts non-AIDS-related morbidity and mortality have been conflicting." (PMID 29851663, 2018). "However, compared to the patients in the TM-negative control group, the HIV/AIDS patients with TM infection had a significantly higher mean CD4+ T cell count (97.05 ± 35.07 vs. 16.15 ± 12.58, p = 0.029) and a higher HIV viral load (6.73 ± 1.64 vs. 6.22 ± 1.26, p = 0.063)." (PMID 30598657, 2018). "The CD4% is also one of the best predictors of AIDS-related events, even after therapy start, and it was highlighted that ECs with CD4% >40% had normal levels of T cell activation and reduced expression of exhaustion markers compared with ECs presenting CD4% <40%." (PMID 30050532, 2018). "In addition to the gender and age differences in HIV/AIDS progression, we further assess the effects of having TB as the initial marker of HIV/AIDS, developing TB during the course of treatment, developing some adverse effects to treatment (Reaction), CD4 baseline and viral load baseline." (PMID 29343268, 2018). "First, we could not provide the association of low CD4/CD8 ratio with each particular non-AIDS incident due to low numbers of events in each category." (PMID 30261902, 2018). "The INSIGHT-START study, for example, found that early ART (initiation at CD4 >500 cells/mm3) reduced the risk of AIDS-related events, non-AIDS related events, and all-cause mortality compared to late ART (initiation at CD4 <350 cells/mm3) by 57% [95% CI: 38–70%]." (PMID 30395635, 2018). "HIV-1 replication in vivo leads to a progressive and selective depletion of CD4+ T lymphocytes leading to the acquired immunodeficiency syndrome (AIDS) in the absence of combination antiretroviral therapy (cART)." (PMID 30250078, 2018). "A greater fraction of adenovirus reads could be measured in AIDS patients with CD4 counts <200." (PMID 30114205, 2018). "Thus, in the context of CD4+ T cell depletion that might reflect the advanced AIDS status, extensive activation and viral replication in macrophages drives a precipitous progression of clinical disease." (PMID 29250073, 2017). "We investigated whether CD4:CD8 ratio and CD8 count were prognostic for all-cause, AIDS, and non-AIDS mortality in virologically suppressed patients with high CD4 count." (PMID 28903507, 2017). "In our study, we also found that a lower CD4+/CD8+ ratio, a detectable viral load and a previous diagnosis of syphilis are associated with a higher risk of having an abnormal cytological finding; subjects with a previous AIDS diagnosis also tended to have a higher risk of cytological abnormalities." (PMID 29088236, 2017). "The success of HAART in delaying acquired immunodeficiency syndrome (AIDS) onset and increasing life expectancy in HIV infected individuals is probably the strongest evidence for a role of viremia in HIV pathology including CD4 T cell decline." (PMID 28829402, 2017).
AIDS (continued). "This is similar to our result which is lower concentration of HDL-C and TC in HIV+TB+ and HIV+TST+ compared to HIV−TB+ and HIV−TST+, respectively, which might be related to the main feature of AIDS, that is, depletion of CD4+ T cells and inhibiting other immune systems." (PMID 29226217, 2017). "The World Health Organization defines “late presentation” (LP) as a new HIV diagnosis with concurrent acquired immunodeficiency syndrome (AIDS) defining events, whatever the CD4+ T cell count, or else a new human immunodeficiency virus (HIV) diagnosis with CD4+ count less than 350 cells/mm3." (PMID 28209189, 2017). "Increasing age, later calendar year, male sex, a lack of history of injection drug use, a lower number of psychosocial barriers, lower CD4 count, increasing viral load, and lack of incident AIDS-defining illness were associated with a shorter time to ART initiation." (PMID 28700693, 2017). "In agreement with our finding of low CD4:CD8 ratio associated with AIDS-related mortality, albeit with wide CIs due to few deaths, an Italian study also found an association of low CD4:CD8 ratio with higher risk of AIDS events and AIDS-related deaths among virally suppressed patients." (PMID 28903507, 2017). "Pneumocystis pneumonia (PCP) in AIDS is often diagnosed empirically based on a subacute onset of cough; breathlessness out of proportion to abnormalities seen on chest radiographs; and subtle, bilateral changes seen on chest radiographs, in the context of a low CD4 cell count." (PMID 27997332, 2017). "However, we found that these parameters could not be used to predict viral load, which remained relatively stable before the AIDS stage, while CD4+ T cell counts declined progressively during the prolonged infection period." (PMID 28979268, 2017). "Our data might have limited generalizability beyond Oregon, given that most patients living with HIV in Oregon have access to care; 87% of all patients in care have a suppressed viral load, and only 16% of AIDS Drug Assistance Program clients lack reported recent CD4 or viral load test results." (PMID 28221103, 2017). "Therefore, the CD4+ diagnostic test is poor for detecting ART failure, and patients’ immune competence would have declined unnoticed as they progressed faster towards clinical failure and AIDS." (PMID 28877173, 2017). "However, in a multivariate Cox model adjusting for other risk factors such as AIDS, CD4 count < 350/μl and hepatitis C, hyponatremia was no longer a predictor for patient death (hazard ratio: 1.03, 95% CI 0.54-1.97; P = 0.935)." (PMID 28122494, 2017). "Finally, we used only CD4+ T-cell counts for the estimation of the number of AIDS incidents, although such an approach still might be imprecise." (PMID 29131849, 2017). "Thus, gene editing using CRISPR/Cas9 may provide a new therapeutic path for eliminating HIV-1 DNA from CD4+ T-cells and potentially serve as a novel and effective platform toward curing AIDS." (PMID 26939770, 2016). "In the delayed group, waiting until a participant’s CD4 T cell counts fell below 200 cells/mm3 or they development of an AIDS-defining condition may have increased the likelihood that a critical irreversible threshold for developing HPV-related disease was exceeded." (PMID 26930571, 2016). "Importantly, the observation of similar rates of CD4+ TCM proliferation and death in SIV-uninfected and infected SMs provides further support to the hypothesis that a preserved CD4+ TCM compartment is central to the ability of SIV-infected SMs to avoid AIDS." (PMID 27227993, 2016). "Interestingly, that patient had CD4+ immunodeficiency, similar as to what occurs in AIDS." (PMID 27528053, 2016). "Therefore, the loss of function of CD4+ T cells due to infections, such as seen in HIV/AIDS, is largely responsible for the impairment of antiviral immunity in the HIV-infected host, which possibly also causes an imbalance in the coordinated immune response with its partner cells." (PMID 27600080, 2016).
AIDS (continued). "Although polyfunctional T cells represent a very low frequency of total CD4+ and CD8+ T cells (in addition to monofunctional T cells) in HIV patients, these cells could lower viral load and have been associated with long-term suppression of AIDS progression." (PMID 27286889, 2016). "However, low CD4+ T-cell counts have not consistently been identified as a risk factor for mortality among persons with AIDS-related cryptococcosis, nor has the number of circulating Cryptococcus-specific CD4+ T lymphocytes." (PMID 26768248, 2016). "In addition, our study evaluated the relationship among the classical markers of AIDS progression, i.e., CD4+ T-cell count, median viral load and cytokine levels, and revealed a correlation between increased viral load and increased IL-6 levels (rho = 0.75, p = 0.02)." (PMID 27214135, 2016). "Importantly, such CD8 elevation in treated HIV infection is associated with an increased risk of inflammatory non-AIDS-related clinical events independent of CD4 T-cell recovery." (PMID 26945343, 2016). "Moreover, such elevation of CD8 counts is associated with an increased risk of non-AIDS-related clinical events, including malignancies and cardiovascular diseases, independent of CD4 T-cell recovery." (PMID 26945343, 2016). "From 2008 onwards, German treatment guidelines recommend initiation of ART at higher CD4-levels This might be an explanation for the observed overall decrease in the proportion of patients presenting to specialized care with AIDS from 1999 to 2013 in our cohort." (PMID 27927190, 2016). "Indeed, in Zimbabwe AIDS patients with probable opportunistic infections, such as TB, present late in the course of their disease at tertiary hospitals as reflected by the low median CD4 counts (55cells/μL) in this study." (PMID 26797499, 2016). "Homeostasis of central memory CD4 T cells is considered a key factor sustaining the asymptomatic stage of Human Immunodeficiency Virus type 1 (HIV-1) infection, while progression to acquired immunodeficiency syndrome is imputed to central memory CD4 T cells homeostatic failure." (PMID 27875993, 2016). "CD4+ T lymphocytes are the most abundant cellular target of HIV-1 in vivo and are widely regarded as the main drivers of viremia, persistence and progression to acquired immunodeficiency syndrome." (PMID 26186441, 2015). "Conversely, a pre-existing AIDS-defining condition or dyslipidaemia at baseline, or a higher diagnosis-to-treatment delay were associated with an increased risk of non-normalization of the CD4/CD8 ratio in the subsequent year." (PMID 26485149, 2015). "The use of WHO clinical staging as an ART eligibility criteria, may not necessarily correlate with immune status (CD4 count) or actual disease progress, especially where diagnostic tests for AIDS defining conditions are not readily available." (PMID 26141729, 2015). "Specifically, CD4+ Th17 cells have been shown to play an important role in mediating the pathogenesis of AIDS following infection, as studies comparing pathogenic and non-pathogenic SIV infection have shown a preferential loss of these cells in pathogenic infections." (PMID 26167159, 2015). "Importantly, Missed Appointments was significantly associated with all clinical outcomes, including CD4 cell count >500 cells/mm3 (negative predictor), progression to AIDS, ED visit, and hospitalization." (PMID 25794182, 2015). "Initiation of HAART with higher CD4+ T-cell count may reduce rate of AIDS progression." (PMID 26413133, 2015). "We did not attempt to stratify CD4 count-specific rates of HIV related symptoms according to age or by other factors which are known to be associated with the progression of AIDS, although such a development could be incorporated to refine the estimates." (PMID 25768925, 2015).
AIDS (continued). "Since HBV vaccine responsiveness has been associated with reduced risk of AIDS or death, it is possible that vaccine responders may have improved immune recovery during cART that is not measured by CD4 counts." (PMID 25928043, 2015). "The critical role for CD4 T cells in the pICLC mediated protection may suggest limited therapeutic implications of type I IFN based therapies for cryptococcosis in AIDS patients, as the most of the HIV-associated cryptococcosis occur as the patients become deficient for CD4 T cells." (PMID 26252005, 2015). "It is also clear in this model that the emergence of escape mutants is neither necessary nor sufficient for the transition to AIDS, but does lead to faster disease progression by precipitating an increase in set-point viraemia and a consequently more rapid loss of CD4+ T cells." (PMID 26150656, 2015). "However, the fact that the observed mortality went from above 35% before to below 13% after the implementation of the simplified test and treat intervention among the subset of patients with CD4 count ≤ 350 cells/mm3 or missing CD4 but reported as AIDS cases is reassuring in this regard." (PMID 26348214, 2015). "However, further investigations are required to elucidate the relationships between serum sodium concentrations and CD4+ cell counts, WHO stages and HIV-RNA levels, and whether hyponatremia is an independent risk factor for death in HIV/AIDS patients." (PMID 25360785, 2014). "We hypothesized that among ART-treated HIV-infected individuals with CD4 counts ≥500 cells/mm3, expansion of CD8+ T cells, reflected as a low CD4/CD8 ratio, may identify individuals with persistent innate and adaptive immune activation at greater risk of serious non-AIDS events." (PMID 24831517, 2014). "Based on the evidence available, VL was proposed—in 1995—as an Acquired Immunodeficiency Syndrome (AIDS)–defining condition requiring ART initiation irrespective of CD4 counts, and this has remained so since then." (PMID 25032826, 2014). "However, HIV/SIV infection is characterized by profound and rapid depletion of CD4 T cells in the gastrointestinal tract, and levels of residual CD4 T cells inversely correlate with maintenance of intestinal architecture and disease progression in AIDS." (PMID 25364618, 2014). "One may consider this progression of HIV infection to AIDS and then to death as a stochastic process, by splitting the progression into various states of the disease based on the immunological indicators, namely CD4+ count, including death as one state." (PMID 25279328, 2014). "However, they also observed accelerated CD4+ T-cell depletion and AIDS progression." (PMID 25077616, 2014). "A higher CD4+ T-cell count (HR, 0.99 per 50 cells/mm3 increase [95% CI.98–.99]), coadministration of TDF with an NNRTI (HR, 0.56 [95% CI.50–.63]), and a previous AIDS-defining event (HR, 0.83 [95% CI.77–.90]) were associated with a decreased likelihood of discontinuing TDF therapy." (PMID 24585896, 2014). "Achieving a CD4 count of over 500 at one point in time conferred a substantial decrease in AIDS or death, while ever having a CD4 count lower than 200 substantially raised the risk of developing AIDS, irrespective of injecting drug use status." (PMID 25523753, 2014). "The observation that hepatic fibrosis is associated with reduced CD4+ T-lymphocytes in HIV-1 positive and negative individuals implies that S. mansoni associated liver pathologies could speed up the progression of HIV to AIDS through the depletion of CD4+ T cells in co-infected individuals." (PMID 23849678, 2013). "QoL was strongly associated with CMD in TB/HIV co-infected patients and HIV/AIDS patients without TB (β = −0.04, P<0.001) after controlling the effect of several confounding variables such as sex, income, CD4 lymphocyte count, adherence to ART and social support." (PMID 23802647, 2013). "Thus CD4+ cell counts are used to stage HIV-AIDS and to initiate antiretroviral therapy." (PMID 24295071, 2013).